EPHA1 (EPH receptor A1)
Description:
Receptor tyrosine kinase which binds promiscuously membrane-bound ephrin-A family ligands residing on adjacent cells, leading to contact-dependent bidirectional signaling into neighboring cells. The signaling pathway downstream of the receptor is referred to as forward signaling while the signaling pathway downstream of the ephrin ligand is referred to as reverse signaling. Binds with a low affinity EFNA3 and EFNA4 and with a high affinity to EFNA1 which most probably constitutes its cognate/functional ligand. Upon activation by EFNA1 induces cell attachment to the extracellular matrix inhibiting cell spreading and motility through regulation of ILK and downstream RHOA and RAC. Also plays a role in angiogenesis and regulates cell proliferation. May play a role in apoptosis.
Synonyms: EPH; EPHT; EPHT1
Tractability: Small molecule: an approved drug acts on it; a high-quality ligand is known; it belongs to a druggable protein family. Antibody: UniProt places it where antibodies can reach, with high confidence; its Gene Ontology location is reachable by antibodies, with high confidence; UniProt predicts a signal peptide or a membrane-spanning region. PROTAC: it is named in the literature on targeted protein degradation; UniProt records ubiquitination sites on it; ubiquitination databases record sites on it; a small molecule that binds it is known.
Target class: Tyrosine protein kinase Eph family; Protein Kinase; TK protein kinase group; Kinase; Enzyme
Gene: Protein-coding gene on chromosome 7 (143,390,289 to 143,408,856, reverse strand). Ensembl gene ENSG00000146904.
Subcellular location: Cell membrane
Pathways (Reactome):
Developmental Biology: EPH-Ephrin signaling; EPH-ephrin mediated repulsion of cells; EPHA-mediated growth cone collapse; POU5F1 (OCT4), SOX2, NANOG activate genes related to proliferation
Gene Ontology:
Molecular function: ephrin receptor activity; fibronectin binding; protein kinase binding; transmembrane-ephrin receptor activity; transmembrane receptor protein tyrosine kinase activity; ATP binding; protein kinase activity; protein tyrosine kinase activity
Biological process: cell surface receptor protein tyrosine kinase signaling pathway; negative regulation of cell migration; positive regulation of angiogenesis; positive regulation of cell migration; positive regulation of cell-matrix adhesion; substrate adhesion-dependent cell spreading; positive regulation of stress fiber assembly; ephrin receptor signaling pathway; regulation of cell adhesion
Cellular component: plasma membrane; receptor complex; membrane
Genetic constraint (gnomAD): Loss-of-function variants: 91 observed, 109.48 expected, observed/expected ratio (o/e) 0.83, 90% interval 0.7 to 0.99. The upper end of that interval is the gene's LOEUF score, 0.99, which puts it in group 4 of 6, group 1 being the genes least tolerant of losing a copy. Missense variants: 1,161 observed, 1,279.3 expected, observed/expected ratio (o/e) 0.91, 90% interval 0.86 to 0.95. Synonymous variants: 476 observed, 514.68 expected, observed/expected ratio (o/e) 0.92, 90% interval 0.86 to 1.
Homologues: Orthologues: chimpanzee EPHA1 (99% identical), macaque EPHA1 (97% identical), pig EPHA1 (90% identical), rabbit EPHA1 (89% identical), mouse Epha1 (88% identical), rat Epha1 (88% identical), dog EPHA1 (88% identical), guinea pig EPHA1 (86% identical). Paralogues in human: EPHA2 (48% identical), EPHA4 (44% identical), EPHB3 (44% identical), EPHA7 (43% identical), EPHA5 (43% identical), EPHA6 (43% identical), EPHB1 (43% identical), EPHA3 (42% identical), EPHB2 (42% identical), EPHA8 (41% identical), EPHB4 (41% identical), EPHA10 (39% identical), and 41 more.
Diseases named in the same sentence as EPHA1 in open-access papers:
EPHA1 is named in the same sentence as 62 diseases in open-access papers, as found by Europe PMC text mining. Sharing a sentence is not in itself a finding about the gene and the disease. The quoted sentences say what the papers report.
Alzheimer disease (14 papers, 2011 to 2025). A progressive, neurodegenerative disease characterized by loss of function and death of nerve cells in several areas of the brain leading to loss of cognitive function such as memory and language. "Here we report the functional consequences of EPHA1 missense mutations identified in Alzheimer’s disease patients, including impaired EPHA1 trafficking, decreased protein stability, and dysregulated canonical and/or noncanonical signaling." (PMID 39706267, 2024). "The six other EPHA1 nonsynonymous coding variants were nominally associated with late-onset Alzheimer’s disease at p > 0.05, with the R791H mutation identified in three families and the others in one or two patients." (PMID 39706267, 2024). "These missense mutations suggest a potential role of EPHA1 in Alzheimer’s disease, highlighting the need to characterize their functional effects." (PMID 39706267, 2024). "Three other independent studies identified an additional EPHA1 rare variant encoding the R492Q mutant as potentially linked to Alzheimer’s disease." (PMID 39706267, 2024). "Our data show that the P460L mutation identified in several Alzheimer’s disease families disrupts EPHA1 function through multiple mechanisms." (PMID 39706267, 2024). "Numerous studies have linked common single nucleotide polymorphisms (SNPs) near the EPHA1 coding region with the risk of late-onset Alzheimer’s disease, but the effects of these SNPs remain poorly understood." (PMID 39706267, 2024). "In an early GWAS of AD, the Alzheimer's Disease Genetics Consortium identified a common variant in EPHA1 associated with AD." (PMID 39233587, 2024). "EPHA1 (Ephrin receptor A1) has recently been identified in large-scale genome-wide association studies to be one of the risk genes for late onset Alzheimer’s disease (AD)." (PMID 23874591, 2013). "In addition, altered alternatively splicing of the EPHB6 gene (located on chromosome 7q34 in the vicinity of the EPHA1 gene) has been associated with Alzheimer’s disease risk and a rare autosomal EPHA6 copy number gain was found to co-segregate with familial Alzheimer’s disease status." (PMID 39706267, 2024). "Interestingly, the P460L mutation might synergize with the higher MMP activity associated with Alzheimer’s disease to increase EPHA1 proteolysis." (PMID 39706267, 2024). "A role for EPHA1 in late-onset Alzheimer’s disease was first proposed almost 15 years ago, but the involvement of this receptor in disease pathogenesis is still poorly understood." (PMID 39706267, 2024). "Given the importance of inflammatory processes in the pathology of Alzheimer’s disease and of the immune system in the clearance of Aβ oligomers, a role of EPHA1 in immune cells seems the most likely." (PMID 39706267, 2024). "MMPs can play diverse roles in neuroinflammation and neurodegeneration, but the importance of MMP-mediated EPHA1 cleavage in Alzheimer’s disease remains to be determined." (PMID 39706267, 2024). "Moreover, a recent study suggests that the EPHA1 V160A and M900V common variants (uniprot.org) may have protective effect in small vessel ischemic disease, a pathology frequently associated with late-onset Alzheimer’s disease." (PMID 39706267, 2024). "A difficulty hindering further investigation of the role of EPHA1 in Alzheimer’s disease is that the cell type(s) affected by EPHA1 signaling are unknown." (PMID 39706267, 2024).
colorectal cancer (13 papers, 2009 to 2022). A primary or metastatic malignant neoplasm that affects the colon or rectum. "On the other hand, in colorectal cancers, low EphA1 expression is associated with shorter survival times, lower histological differentiation, and the presence of lymph node metastasis." (PMID 33007931, 2020). "Contrary to our study, a lower EPHA1 protein expression was linked to aggressive tumor features and shorter survival in colorectal carcinomas." (PMID 25025847, 2014). "As in the case of EphA1 and EphA2, initial upregulation of EphB2 and EphB3 expression appears to be followed by a loss of expression in the more advanced metastatic stages of colorectal cancer." (PMID 33430066, 2021). "Reduced EPHA1 expression was associated with poorly differentiated and invasive tumors and poor overall survival, indicating that EPHA1 may play different roles during different stages of colorectal carcinoma progression." (PMID 25193853, 2014). "In support of this, lower expression of EphA1 was correlated with shorter survival in colorectal cancer patients." (PMID 33430066, 2021). "In slight contrast to the distinct upregulation or downregulation already mentioned in breast cancer (see Section 3), the expression levels of EphA1 and EphA2 were found to differ between the stages of colorectal cancer." (PMID 33430066, 2021). "Many studies have observed an altered expression of Eph receptors in colorectal cancers, especially for EphA2, EphA1, EphB4, and EphB2." (PMID 32316101, 2020). "Low EPHA1 expression strongly correlates with poor survival in colorectal cancer and its downregulation correlates with invasion and metastasis." (PMID 31412533, 2019). "On the other hand, therapies targeting EPHA1 in colorectal cancer should be carefully evaluated since this gene seems to play different roles during disease progression." (PMID 25193853, 2014). "We describe EphA1 expression in 6 colorectal cancer (CRC) cell lines, 18 controls and 125 CRC specimens." (PMID 19277044, 2009). "The expression level of EphA1 and its association with clinical parameters are factors that have been analyzed for various tumors, including gastric cancer, colorectal cancer, non-melanoma skin cancer, and squamous cell carcinoma." (PMID 34221956, 2021). "Point mutations in EPHA2 and EPHA1 have not so far been described in the literature for colorectal cancer." (PMID 25193853, 2014). "Since EGFR, EphA1, and EphA2 positively correlated with Ephexin1 in both colon and lung tissues, we focused on these three proteins and analyzed the survival rates of lung cancer and colorectal cancer patients relative to the expression levels of all four proteins." (PMID 35668076, 2022).
gastric cancer (8 papers, 2003 to 2023). A primary or metastatic malignant neoplasm involving the stomach. "EphA1 was overexpressed in gastric cancer, and its expression level was significantly associated with poor prognosis." (PMID 35770949, 2023). "In gastric cancer, high expression of EphA1 is associated with lower tumor histological differentiation, the presence of lymph node and distant metastasis." (PMID 33007931, 2020). "This is in line with studies in esophageal and gastric cancers, where a lower EPHA1 protein expression was significantly associated with less aggressive tumor features like lower tumor stage, absence of lymph node metastases and lower grade." (PMID 25025847, 2014). "In line with our results, a longer survival was also reported for gastric carcinoma patients with low EPHA1 protein levels." (PMID 25025847, 2014). "We found that expressions of eph (ephA1) and hek5 (ephB2) were upregulated following treatment in several gastric cancer cell lines." (PMID 12671705, 2003). "For example, EphA1 and EphA4 are upregulated in gastric cancer; EphA2 overexpression in mammary epithelial cells induces tumorigenesis and EphA8 stimulates the proliferation, invasion, and migration of gastric cancer cells." (PMID 35681118, 2022). "In gastric cancers, high expression of EphA1 is an independent prognostic factor." (PMID 33007931, 2020). "EPHA1, EPHA2, EPHA3, EPHA5, EPHB2 and EPHB4 expression has been reported as 2-fold higher in stromal cells isolated from gastric cancer tissues compared with normal gastric tissue stromal cells." (PMID 34445116, 2021). "Among these cytokines, Notch‐3, galectin‐8, EphA1, epiregulin, and FGF‐12 have been reported to be upregulated in gastric cancer." (PMID 30873760, 2019).
hepatocellular carcinoma (8 papers, 2016 to 2024). A malignant tumor that arises from hepatocytes. "EphA1 was the first discovered Eph receptor tyrosine kinase and was cloned in 1987 from a hepatocellular carcinoma (HCC) cell line; next, in 1990 the screening of a cDNA library of HeLa cells brought the identification of EphA2." (PMID 36142306, 2022). "The first member, named EphA1, was cloned from an erythropoietin-producing hepatocellular cancer cell line and the second member, EphA2, was identified by screening the human epithelial (Hela cells) cDNA library." (PMID 28752098, 2017). "EPHA1 (OMIM*179610) is a receptor tyrosine kinase gene, and overexpression of oncogene EPHA1 was found in hepatoma and lung cancer." (PMID 38540211, 2024). "EFNA1-induced EphA1 activation promotes SDF-1 secretion and endothelial progenitor cell chemotaxis to hepatocellular carcinoma through the SDF-1/CXCR4 signalling pathway." (PMID 34344926, 2021). "Therefore, we investigated the role of EphA1 in EPCs’ chemotaxis and tube formation potency in HCC cells through manipulating EphA1 gene expression in HLE cells (EphA1 low expression hepatoma cells) and Huh-7 cells (EphA1 high expression hepatoma cells)." (PMID 27066828, 2016).
lung carcinoma (8 papers, 2014 to 2024). "Among the SVZM+ exclusive mutations identified in the TCGA cohort, the ephrin family member EPHA1 mutation may provide an interesting therapeutic target as it was recently attributed to an improved response to anti-PD-L1 immune checkpoint inhibition in lung cancer." (PMID 35660939, 2022). "The combined expression of EphA1, EphA4, EphA5, and EphA7 has been used to distinguish various stages of lung cancer." (PMID 29682554, 2018). "In an analysis of survival rates among lung cancer patients, the higher the expression of Ephexin1, EGFR, EphA1, and EphA2, the lower the rate." (PMID 35668076, 2022). "The expression levels of EphA1, EphA4, EphA5 and EphA7 have been investigated in patients with nonsmall cell lung carcinoma (NSCLC), the most common type of lung cancer." (PMID 33430066, 2021). "In Palbociclib resistant lung cancer cells, an increased activation of several receptor kinases was observed, such as epidermal growth factor receptor (EGFR), ephrin type-A receptor 1/2 (EphA1/2) and fibroblast growth factor receptor (FGFR)." (PMID 35712501, 2022).
breast carcinoma (5 papers, 2018 to 2023). "A previous report showed that EPHA1 downregulation is associated with the invasiveness of breast carcinoma cells." (PMID 33977106, 2021). "In the UALCAN database, the mRNA expression of EPHA1, EPHA10, EFNA1, EFNA3, and EFNA4 was significantly higher, whereas that of EPHA2, EPHA4, EPHA5, and EFNA5 was significantly lower in breast cancer tissues than in paracancerous tissues." (PMID 33977106, 2021). "Similarly, well characterized kinases known for their relevance in breast cancer are observed, such as ERBB2, EPHA1, MET and TGFBR2." (PMID 29643987, 2018).
prostate carcinoma (5 papers, 2016 to 2021). A carcinoma that arises from epithelial cells of the prostate gland. "Temporal context is also an important consideration as it is possible for there to be different levels of expression for different stages of disease such as is the case for EphA1 in colorectal and prostate cancer." (PMID 33430066, 2021). "While EphA1 abundance was decreased in prostate cancer cell lines, EphA2, EphA5, EphA6, EphA7, EphA8, and EphA10 levels were elevated in some of the prostate cancer cell lines as compared to the normal prostate cell line." (PMID 29682554, 2018). "We observed elevated tyrosine autophosphorylation levels upon deletion of the EphA2 SAM domain (EphA2ΔS) in DU145 and PC3 prostate cancer cells and a skin tumor cell line derived from EphA1/A2 knockout mice." (PMID 28338017, 2017). "While the expression levels of other EphA receptors seem to be upregulated in prostate cancer, the expression of EphA1 was shown to be downregulated, decreasing from normal prostate to primary prostate tumour cells and finally to metastatic cells, possibly due to CpG methylation of the promoter." (PMID 33430066, 2021). "EphA1, the first identified Eph family member, is physiologically expressed in epithelial tissues, and its pathological overexpression has been reported in a variety of tumors, including gastric cancer, liver cancer, prostate cancer, and esophageal squamous cell carcinoma." (PMID 27066828, 2016).
squamous cell carcinoma (4 papers, 2009 to 2021). A carcinoma arising from squamous epithelial cells. "Cancer tissues exhibited downregulation of EPHA1 in relation to normal tissues, and EPHA1 decreased expression associated with increased tumor thickness in squamous cell carcinoma cases." (PMID 34445116, 2021). "In squamous cell carcinoma of the tongue, high expression of EphA1 is associated with poorer tumor vasculature and less frequent lymph node metastasis." (PMID 33007931, 2020). "A recent study demonstrated significant downregulation of EphA1 in basal cell and squamous cell carcinomas, through immunohistochemistry." (PMID 19277044, 2009). "EPHA1 expression in 56 basal cell and 32 squamous cell carcinoma was examined through IHC and q RT-PCR and compared to 10 normal skin tissues." (PMID 34445116, 2021).
clear cell renal cell carcinoma (3 papers, 2014 to 2023). "In clear-cell renal cell carcinoma, high expression of EphA1 is significantly associated with young age, sex, and higher histopathological grade." (PMID 33007931, 2020). "In this study, mRNA and protein expression of the receptors EPHA1 and EPHA2 as well as of their ligand EFNA1 and their prognostic relevance in clear cell renal cell carcinoma was evaluated." (PMID 25025847, 2014).
liposarcoma (3 papers, 2017 to 2024). A usually painless malignant tumor that arises from adipose tissue. "In a previous large-scale genomic sequencing study of soft tissue sarcoma specimens, that included 50 DD liposarcomas, a different CTNNB1 (T41I) mutation was described in a DD liposarcoma, including 3 other nonrecurring mutations (CDH1 (N238D), EPHA1 (A2127) and FBXW7 (E113fs))." (PMID 29731991, 2018).
glioma (2 papers, 2016 to 2024). A benign or malignant brain and spinal cord tumor that arises from glial cells (astrocytes, oligodendrocytes, ependymal cells). "In the RMPAlow gliomas, a different set of RTK signaling-related genes including MET (8.9%), EPHA1 (8.9%), EPHB6 (8.9%), EPHB4 (8.3%), BRAF (8.9%), FGF6 (11.9%), FGF23 (11.9%), NTF3 (11.9%), and ANGPT1 (9.5%) were amplified." (PMID 27385209, 2016).
lymph node metastases (2 papers, 2020 to 2025). "In esophageal squamous cell carcinoma, elevated expression of EphA1 is associated with presence of lymph node metastasis and more advanced disease." (PMID 33007931, 2020). "High expression of EphA1 was significantly linked to the absence of vascular invasion and lymph node metastases." (PMID 40421081, 2025).
melanoma (2 papers, 2016 to 2023). A malignant, usually aggressive tumor composed of atypical, neoplastic melanocytes. "EPHA1, EPHA3 and EPHB6 were contained in regions of copy gain, suggesting their oncogenic role during melanoma progression." (PMID 27095580, 2016).
non-small cell lung carcinoma (2 papers, 2014 to 2018). A group of at least three distinct histological types of lung cancer, including non-small cell squamous cell carcinoma, adenocarcinoma, and large cell carcinoma. "The present study aimed to evaluate the clinical significance of EphA1, A4, A5 and A7 protein expression in non-small cell lung carcinoma (NSCLC)." (PMID 24495444, 2014).
ovarian carcinoma (2 papers, 2006 to 2020). A malignant neoplasm originating from the surface ovarian epithelium. "EphA1 and EphA2 over-expression was correlated with ephrin A1 suggesting that their interaction may have a role in ovarian cancer progression." (PMID 16737551, 2006).